PTPN22 (protein tyrosine phosphatase non-receptor type 22)
Diseases named in the same sentence as PTPN22 in open-access papers (continued):
Sharing a sentence is not in itself a finding about the gene and the disease.
autoimmune disease (continued). "It seems likely that the finding of clustering of autoimmune diseases in individuals is contributed to by shared genetic susceptibility loci at immune regulatory genes (HLA, CTLA-4, PTPN22 and CD40)." (PMID 29529281, 2018). "This deficiency in immunological tolerance explains the significance of PTPN22 in the development of autoimmune diseases." (PMID 27215233, 2017). "In unravelling possible new pathways to future trials for the treatment of autoimmune diseases in humans, our approach aimed to allow T cell specific down-regulation by using antisense strand complementary to the mRNA of PTPN22." (PMID 28437437, 2017). "Altogether, these results confirm the direct involvement of PTPN22 gene independently of HLA locus in the pathogenesis of autoimmune diseases." (PMID 28210620, 2017). "In this study, we examined the influence of the phosphatase PTPN22 on the development of autoimmune disease in combination with an established model of autoimmune arthritis, the SKG mouse." (PMID 27288531, 2016). "Autoimmune diseases are known to share a common genetic architecture, with some loci, such as CTLA4, PTPN22, and the HLA, conferring susceptibility to multiple autoimmune diseases." (PMID 27680876, 2016). "The gene networks identified contain hallmark genes for each category, for example, PTPN22 and MHC genes for polygenic autoimmune diseases and NOD2 for polygenic autoinflammatory diseases." (PMID 27964755, 2016). "In this article, we present an analysis of PTPN22 function in the neutrophil, concentrating on FcγR signaling owing to its prominent role in autoimmune diseases." (PMID 27807193, 2016). "Known autoimmune disease risk loci, such as the MHC and PTPN22, have been associated with multiple autoimmune diseases such as type 1 diabetes, CD, and MS." (PMID 27812365, 2016). "Taken together, our data strengthen STAT4 rs7574865 G/T and PTPN22 rs2488457 G/C polymorphisms as susceptibility factors for JIA and provide further evidence for a common origin of autoimmune diseases." (PMID 25781893, 2015). "At least seven of these are involved in autoimmune diseases or immune cell function: Ptpn22, Adora3, Rbm15, Lrig2, Cd53, Nras, and a cluster of six chitinase-like genes." (PMID 26438525, 2015). "PTPN22/CSK pathway has been postulated as a potential common genetic factor shared for different autoimmune disorders." (PMID 26458874, 2015). "For example, the gene PTPN22 showed pleiotropic effects in multiple autoimmune diseases including T1D, SLE and RA." (PMID 26253105, 2015). "Based on this theory, the PTPN22 function in autoimmune disease manifestations seems to affect generation and activation of immune cells." (PMID 25452756, 2014). "PTPN22 is a phosphatase that suppresses lymphocyte activation, and is a risk factor for SLE as well as other autoimmune diseases." (PMID 25147296, 2014). "The two most investigated genes, which are potentially associated with autoimmune diseases are CTLA-4 and PTPN22." (PMID 25452756, 2014). "The PTPN22 rs2476601 (R620W) polymorphism has been found to be associated with GPA and with multiple other autoimmune diseases." (PMID 25452756, 2014). "PTPN22 has strong functional consequences for immune responses, supporting evidence of association with SLE and other autoimmune diseases." (PMID 23950893, 2013). "Bottini N and co-workers suggested the use of PTPN22 SNPs as a prognostic factor for disease severity and variability in autoimmune diseases, but also requested further studies taking this point under investigation." (PMID 21429197, 2011). "It is now clear that immune-regulatory genes such as HLA, CTLA-4, and PTPN22 play a major role in the aetiology of HT, GD, and several other autoimmune diseases." (PMID 22654557, 2011). "Accumulating evidence of shared susceptibility loci among the autoimmune diseases has directed a number of other gene discovery efforts in AITD, including PTPN22, now a well-established general autoimmune risk locus." (PMID 22654554, 2011).
autoimmune disease (continued). "It has been suggested that the Trp620 allele is implicated in autoimmune diseases associated with autoantibody production, such as AAV or T1D, and indeed the Trp620 allele of rs2476601 in PTPN22 is associated with both WG and MPA." (PMID 19951419, 2009). "However, research on PTPN22 has primarily focus on autoimmune diseases and the immune system, with limited studies examining its role in tumor cells." (PMID 41522360, 2026). "The second hypothesis is supported by recent genetic studies, which have identified shared susceptibility loci, such as CTLA4, PTPN22, and TNFAIP3, across multiple autoimmune diseases." (PMID 40725836, 2025). "Protein tyrosine phosphatase nonreceptor type 22 (PTPN22) is encoded by a gene strongly associated with lupus and other autoimmune diseases." (PMID 40911684, 2025). "Collectively, these findings suggest that PTPN22 promotes the development of autoimmune diseases." (PMID 39944077, 2025). "Protein tyrosine phosphatase non-receptor type 22 (PTPN22) gene is a major genetic risk factor for a number of autoimmune diseases." (PMID 40305360, 2025). "Several genetic variations, e.g., PTPN22 and CTLA-4 polymorphisms, might predispose simultaneously to the development of AD, RA, and other systemic and organ-specific autoimmune diseases." (PMID 40507712, 2025). "Additionally, key genes such as IL2RA and CD247, linked with risk genes PTPN22, PTPN2, and RUNX1, are consistently implicated across multiple conditions, including RA, lupus erythematosus, B-cell lymphomas, and autoimmune diseases." (PMID 40839671, 2025). "PTPN22 has well-established genetic links to various autoimmune disorders, including AITD." (PMID 39337081, 2024). "Other genes associated with autoimmune disease susceptibility include those involved in immune cell signaling and activation, such as protein tyrosine phosphatase non-receptor type 22 (PTPN22), CTLA-4, and CD40." (PMID 39062908, 2024). "One of the first candidate-gene studies focused on protein tyrosine phosphatase non-receptor type 22 (PTPN22), a gene which is involved in T-cell receptor signaling that showed associations in families affected by multiple autoimmune disorders." (PMID 39057087, 2024). "PTPN22 R620W, hereafter referred to as the PTPN22 risk variant, is one of the strongest, non-HLA, genetic risk factors for autoimmune diseases, nearly doubling a carrier’s risk of type 1 diabetes, systemic lupus erythematosus, or rheumatoid arthritis." (PMID 36961507, 2023). "Outside the HLA region, one of the most prominent genetic contributors to autoimmune diseases, including type 1 diabetes mellitus, is protein tyrosine phosphatase, nonreceptor type 22 (PTPN22), which encodes lymphoid tyrosine phosphatase (LYP)." (PMID 37315092, 2023). "As PTPN22 plays a role in multiple autoimmune diseases, it has been argued that this SNP potentially highlights a common pathway that alters immune tolerance and might serve as a potential point of intervention to prevent and/or delay disease." (PMID 36961507, 2023). "Polymorphisms in genes involved in other autoimmune disorders, including cytotoxic T-lymphocyte associated protein 4 (CTLA-4) and protein tyrosine phosphatase non-receptor type 22 (PTPN22) among others, have been identified as additional risk factors for APS-2." (PMID 36980146, 2023). "In addition, we need to combine basic research with clinical disease to explore how the effects of PTPN22 on T cell development regulate the pathogenesis of autoimmune diseases such as type 1 diabetes, systemic lupus erythematosus, and rheumatoid arthritis." (PMID 37833951, 2023). "Other genetic variations intensively studied regarding their association with autoimmune diseases, in particular, SLE, were the R620W polymorphism of the protein tyrosine phosphatase non-receptor type 22 gene (PTPN22), MYO9B, and CLEC16A (chromosomal position 16p13)." (PMID 37299501, 2023).
autoimmune disease (continued). "The rs2476601 variant in the coding region of the protein tyrosine phosphatase non-receptor type 22 (PTPN22) gene is one of the most strongly associated risk variants shared across autoimmune diseases including RA, T1D, and SLE." (PMID 35979360, 2022). "In this context, PTPN22 is one of the most important non-HLA genes, which has been associated with various autoimmune diseases, including rheumatoid arthritis, type 1 diabetes mellitus, and SLE." (PMID 36428917, 2022). "Here, we review how genetic variants shared across multiple autoimmune diseases have contributed to our understanding of global tolerance failure, focusing on variants in the human leukocyte antigen region, PTPN2 and PTPN22, and their role in antigen presentation and T and B cell homeostasis." (PMID 35979360, 2022). "Csk homodimer formation could limit the abundance of WT PTPN22/Csk complexes and contribute to PTPN22 R620W autoimmune disease." (PMID 35393453, 2022). "The protein tyrosine phosphatase non-receptor 22 gene (PTPN22) is one of the candidate susceptibility genes for autoimmune diseases." (PMID 36013501, 2022). "Even for non-organ specific autoimmune diseases of complex pathogenesis, the association with the PTPN22 polymorphism was observed in Caucasians, that is, SLE (rev." (PMID 35008834, 2021). "In addition to loci implicated in lymphocyte function and development shared with other autoimmune diseases such as HLA, BACH2, PTPN22 and CTLA4, we associate two protein-coding alterations in Autoimmune Regulator (AIRE) with AAD." (PMID 33574239, 2021). "Among the genetic variants associated with several autoimmune disorders, the C1858T polymorphism of the protein tyrosine phosphatase non-receptor type 22 (PTPN22) gene, encoding for Lyp variant R620W, affects the innate and adaptive immunity." (PMID 35008834, 2021). "PTPN22-C1858T is more often discussed in autoimmune disease." (PMID 33717071, 2021). "Protein tyrosine phosphatase, non-receptor type 22 (PTPN22) was identified as the susceptibility gene for SSc by the GWAS as well as for a wide range of autoimmune diseases." (PMID 34130729, 2021). "Similar to our findings, both the PTPN22 rs2476601 and CTLA4 rs3087243 risk variants were shown to be susceptibility loci for autoimmune diseases including anti-neutrophil cytoplasmic antibody (ANCA)-associated vasculitis (AAV) and autoimmune polyglandular autoimmunity." (PMID 32328064, 2020). "The PTPN22 SNP rs2476601 is one of the most important susceptibility loci for autoimmunity and is associated with myasthenia gravis (MG), type 1 diabetes (T1D), systemic lupus erythematosus (SLE), rheumatoid arthritis (RA), and other autoimmune disorders." (PMID 32328064, 2020). "PTPN22 polymorphism was implicated in the risk for various autoimmune diseases including type 1 diabetes (T1D) but not for celiac disease (CD)." (PMID 30915320, 2019). "The role of the pleiotropic 1858C/T of PTPN22 may suggest common and shared immune functions in various autoimmune diseases." (PMID 30871019, 2019). "The protein tyrosine phosphatase nonreceptor type 22 (PTPN22) exhibits a common single nucleotide polymorphism (SNP), C1858T, which has been strongly linked with autoimmune disorders." (PMID 30483260, 2018). "Single nucleotide polymorphisms (SNP) in the protein tyrosine phosphatase nonreceptor type 22 gene (PTPN22) encoding the lymphoid protein tyrosine phosphatase LYP were found to be associated with several autoimmune disorders." (PMID 28210620, 2017). "The autoimmune predisposing allele of protein tyrosine phosphatase non-receptor 22 (PTPN22) has attracted a lot of attention due to its association with several autoimmune diseases such as type 1 diabetes and rheumatoid arthritis." (PMID 28747914, 2017).
autoimmune disease (continued). "A genetic variant of the protein tyrosine phosphatase non-receptor 22 (PTPN22) is associated with a wide range of autoimmune diseases; however, the reasons behind its prevalence in the general population remain not completely understood." (PMID 28747914, 2017). "Although several studies have reported the relationship between STAT4 and PTPN22 gene SNPs and some others autoimmune diseases, to date, less study focused on relation of STAT4 and PTPN22 gene polymorphisms and type 1 AIH risk previously, particularly for Chinese children." (PMID 28977835, 2017). "There are various Single-nucleotide polymorphisms (SNP) of PTPN22 gene affecting many autoimmune diseases but do not carry the same risk." (PMID 27215233, 2017). "Genome-wide association studies have established that the gene encoding the protein tyrosine phosphatase nonreceptor 22 (PTPN22) makes an important contribution to susceptibility to autoimmune disease, notably rheumatoid arthritis." (PMID 27807193, 2016). "A non-synonymous SNP, rs2476601 (also referred to as C1858T or R620W), located in the gene encoding protein tyrosine phosphatase nonreceptor 22 (PTPN22) has been repeatedly associated with a wide range of autoimmune diseases, including JIA." (PMID 27107590, 2016). "Protein tyrosine phosphatase nonreceptor 22 (PTPN22) is a leukocyte-restricted phosphatase associated with an increased risk in a range of autoimmune diseases, notably RA." (PMID 27807193, 2016). "Together these results indicate that signaling through PTPN22 can influence cytokine production in T cells expressing WT ZAP70 in addition to the SKG mutation, and that this may influence susceptibility to autoimmune disease." (PMID 27288531, 2016). "Ptpn22 is a strong candidate for causing the susceptibility associated with the B6-derived alleles of Idd18.2, because the human homolog PTPN22 contains a nonsynonymous R620W polymorphism that is associated with several autoimmune diseases, including T1D." (PMID 26438525, 2015). "The protein tyrosine phosphatase non-receptor 22 (PTPN22) R620W gene polymorphism is a general risk factor for autoimmune diseases with an increased production of auto-antibodies and predisposes MG and EOMG in particular for additional autoimmune diseases." (PMID 25915571, 2015). "Despite these observations, it is still unclear whether the expression of PTPN22 in patients with autoimmune diseases differs from that of healthy individuals, and how this would occur." (PMID 24433447, 2014). "PTPN22 has been shown to be one of the strongest non-HLA susceptibility genes for various autoimmune diseases, such as rheumatoid arthritis (RA), type 1diabetes (T1D), systemic lupus erythematosus (SLE), and Graves' disease (GD)." (PMID 24816862, 2014). "The protein tyrosine phosphatase gene (Ptpn22) is of particular interest, as in humans a mis-sense SNP (C1858T) has already demonstrated strong correlation with rheumatoid arthritis, type-1 diabetes mellitus, and other autoimmune disease." (PMID 23442222, 2013). "The risk allele of PTPN22, a major autoimmune susceptibility gene of GD and several other autoimmune diseases in Caucasians, is non-polymorphic in Asians." (PMID 21307958, 2011). "The minor allele (T) at 1858C>T (rs2476601) single-nucleotide polymorphism (SNP) in the protein tyrosine phosphatase non-receptor type 22 (PTPN22, gene map locus 1p13) gene has been extensively associated with susceptibility to various autoimmune diseases." (PMID 21949702, 2011). "Protein tyrosine phosphatase type 22 (PTPN22) and Cytotoxic T lymphocyte antigen-4 (CTLA-4) are two of these genes, and single nucleotide polymorphisms (SNPs) in the genes encoding these molecules have been associated with several autoimmune diseases." (PMID 19180256, 2009). "In contrast, PTPN22 R620W has not been associated with two other presumed autoimmune disorders, multiple sclerosis and Crohn’s disease." (PMID 19180256, 2009).
autoimmune disease (continued). "Polymorphisms of the protein tyrosine phosphatase non-receptor 22 gene (PTPN22) have recently been reported to be associated with susceptibility to several autoimmune diseases." (PMID 19503742, 2009). "The combination of the PTPN22 1858T variant and anti-CCP antibodies was found only among pre-patients, making it a strong predictor for the development of RA, possibly by influencing the progression of an overt autoimmune disease." (PMID 16507117, 2006). "The protein tyrosine phosphatase non-receptor type 22 (PTPN22) gene encodes the lymphoid-specific tyrosine phosphatase (Lyp) and a genetic single-nucleotide polymorphism of PTPN22 rs2476601 (R620W) has been associated with several human autoimmune diseases, including rheumatoid arthritis (RA)." (PMID 39724988, 2024). "The leading example for such a genetic predisposition in human disease is the LOF variant of the protein tyrosine phosphatase non-receptor 22 (PTPN22), which is highly associated with several autoimmune diseases including SLE, autoimmune diabetes mellitus, and rheumatoid arthritis." (PMID 38885295, 2024). "This study investigates quercetin, a natural compound found in many fruits and vegetables, for its potential to inhibit the phosphomonoesterase activity of protein tyrosine phosphatase nonreceptor type 22 (PTPN22), a key immune response regulator implicated in cancer and autoimmune diseases." (PMID 39451542, 2024). "Similarly, polymorphisms in the listed genes VAV3, SH2B3, FOXE1 and PTPN22 were identified in the 23andMe database to be associated not only with hypothyroidism but also with other autoimmune diseases." (PMID 38919955, 2024). "Therefore, our dataset informs on a single signaling program and PTPN22 may contribute to autoimmune disease via other pathways." (PMID 36961507, 2023). "In addition, the results of this study may facilitate the development of new combinatorial therapies for autoimmune disease that target both UBASH3A and PTPN22 or the key molecular pathways involving these two risk factors." (PMID 37240014, 2023). "Among the others, the C1858T polymorphism of the protein tyrosine phosphatase non-receptor type 22 (PTPN22) gene is associated with several autoimmune diseases; this encodes for a more active phosphatase, namely the Lyp variant R620W, which is a potent inhibitor of T-cell activation." (PMID 35683627, 2022). "In summary, our results show how the activity of PTPN22, a gene where a risk variant is associated with autoimmune diseases, can be regulated by ROS through its noncatalytic C129 residue, which is likely to have a major impact on its function in addition to that of merely altered basal turnover." (PMID 35587260, 2022). "Interestingly, the results of comprehensive meta-analysis showed no or weak association of PTPN22 rs2476601 with CD and some autoimmune diseases primarily affecting the gastrointestinal system." (PMID 30915320, 2019). "In addition, further studies should be performed to elucidate how PTPN22 1858 C/T could influence the pathogenesis of each autoimmune disease." (PMID 30871019, 2019). "One aspect of the role of PTPN22 in autoimmune diseases may lie in its function in T cells." (PMID 30483260, 2018). "A single nucleotide polymorphism, C1858T, in the gene encoding the protein tyrosine phosphatase nonreceptor type 22 (PTPN22) results in one of the strongest genetic traits associated with autoimmune disease outside of the Major Histocompatibility Complex (MHC) genes." (PMID 30483260, 2018). "Interestingly, RA is a systemic autoinflammatory disease which is associated with PTPN22/C1858T, while the organ-specific autoimmune disease CD is not." (PMID 26090488, 2015). "Among the non-HLA genetic associations with autoimmune diseases, the PTPN22 R620W gene polymorphism was shown to be a major risk factor in association studies of several diseases in Caucasian populations including North American, Spanish, British, Dutch, French-Canadian and Swedish patients." (PMID 25119822, 2014).